CLDN20 (claudin 20)
Description:
Plays a major role in tight junction-specific obliteration of the intercellular space, through calcium-independent cell-adhesion activity.
Tractability: Antibody: its Gene Ontology location is reachable by antibodies, with high confidence; UniProt places it where antibodies can reach, with medium confidence; UniProt predicts a signal peptide or a membrane-spanning region.
Gene: Protein-coding gene on chromosome 6 (155,264,013 to 155,276,548, forward strand). Ensembl gene ENSG00000171217.
Subcellular location: Cell junction, tight junction; Cell membrane
Subcellular location (Human Protein Atlas): Golgi apparatus; Plasma membrane; Cytosol
Pathways (Reactome):
Cell-Cell communication: Tight junction interactions
Gene Ontology:
Molecular function: protein binding; identical protein binding; structural molecule activity
Biological process: calcium-independent cell-cell adhesion
Cellular component: plasma membrane; tight junction; bicellular tight junction; membrane
Genetic constraint (gnomAD): Loss-of-function variants: 0 observed, 1.09 expected, observed/expected ratio (o/e) 0, 90% interval 0 to 1.7. That is too few expected variants to judge how well the gene tolerates losing a copy. Missense variants: 246 observed, 265.98 expected, observed/expected ratio (o/e) 0.92, 90% interval 0.83 to 1.03. Synonymous variants: 99 observed, 101.46 expected, observed/expected ratio (o/e) 0.98, 90% interval 0.83 to 1.15.
Homologues: Orthologues: chimpanzee CLDN20 (100% identical), macaque CLDN20 (98% identical), dog CLDN20 (89% identical), pig CLDN20 (83% identical), rabbit CLDN20 (81% identical), guinea pig CLDN20 (79% identical), rat Cldn20 (77% identical), mouse Cldn20 (74% identical). Paralogues in human: CLDN7 (36% identical), CLDN1 (35% identical), CLDN14 (35% identical), CLDN9 (35% identical), CLDN2 (34% identical), CLDN19 (33% identical), CLDN3 (32% identical), CLDN4 (32% identical), CLDN17 (32% identical), CLDN6 (31% identical), CLDN5 (30% identical), CLDN8 (28% identical), and 10 more.
Diseases named in the same sentence as CLDN20 in open-access papers:
CLDN20 is named in the same sentence as 12 diseases in open-access papers, as found by Europe PMC text mining. Sharing a sentence is not in itself a finding about the gene and the disease. The quoted sentences say what the papers report.
breast carcinoma (3 papers, 2018 to 2025). "We have previously studied the role of claudins and tight junction molecules including CLDN19, CLDN20, and ZOs in breast cancer." (PMID 38137355, 2023). "For example, CLDN1, CLDN3, CLDN7, CLDN16 and CLDN20 have been found to be downregulated in breast cancer, and the downregulation of these claudins appearing to be linked to a more aggressive phenotype and with poor clinical outcome." (PMID 38137355, 2023). "Claudin-20, for example, a tight junction protein in the epithelium, is correlated with poor prognosis of breast cancer patients, likely through its increased migratory effect on cancer cells." (PMID 29867202, 2018). "CLDN5 is tightly regulated at the blood-brain-barrier and is compromised in several neurological diseases, while in breast-cancer models, overexpression of CLDN20 increases trans-epithelial electrical resistance (TEER), both tissue-specific roles highlighting the complex nature of claudins." (PMID 40260206, 2025).
brain cancer (1 paper, 2006). A primary or metastatic malignant neoplasm affecting the brain. "CLDN20 was only found in 3 cancer libraries total (a chondrosarcoma, a brain cancer, and a liver tumor)." (PMID 16836752, 2006).
E. coli infection (1 paper, 2020). "Six genes (CLDN20, PARD6B, CD151, CDH11, CLDN2 and F11R) related to the GO biological process “Cell junction organization” were upregulated by E. coli infection, whereas these genes were not induced by EPS." (PMID 32234079, 2020).
periodontitis (1 paper, 2023). An acute or chronic inflammatory process that affects the tissues that surround and support the teeth. "By taking the intersection of WGCNA important module genes and DEGs, we found that the SPAG4, CCDC69, KRT10, CXCL12, HPGD, CLDN20 and CCL187 genes were the most important cross-talk genes between periodontitis and IgAN." (PMID 36793719, 2023). "The SPAG4, CCDC69, KRT10, CXCL12, HPGD, CLDN20 and CCL187 genes were the most important cross-talk genes between periodontitis and IgAN." (PMID 36793719, 2023). "By taking the intersection of WGCNA important module genes and DEGs, we found that the SPAG4, CCDC69, KRT10, CXCL12, HPGD, CLDN20 and CCL187 genes were the most important cross-talk genes between periodontitis and IgAN, and these genes may be related to kinase regulator activity." (PMID 36793719, 2023).
CLDN20 also shares sentences with these, for which no sentence is quoted: cancer (2 papers); cardiovascular disease (1); chondrosarcoma (1); hepatocellular carcinoma (1); neurological diseases (1); Obesity (1); tumor (1); type 2 diabetes (1).